CDK5RAP2 (CDK5 regulatory subunit associated protein 2)
Description:
Potential regulator of CDK5 activity via its interaction with CDK5R1. Negative regulator of centriole disengagement (licensing) which maintains centriole engagement and cohesion. Involved in regulation of mitotic spindle orientation (By similarity). Plays a role in the spindle checkpoint activation by acting as a transcriptional regulator of both BUBR1 and MAD2 promoter. Together with EB1/MAPRE1, may promote microtubule polymerization, bundle formation, growth and dynamics at the plus ends. Regulates centrosomal maturation by recruitment of the gamma-tubulin ring complex (gTuRC) onto centrosomes. In complex with PDE4DIP isoform 13/MMG8/SMYLE, MAPRE1 and AKAP9, contributes to microtubules nucleation and extension from the centrosome to the cell periphery. Required for the recruitment of AKAP9 to centrosomes. Plays a role in neurogenesis (By similarity).
Synonyms: CEP215; C48; FLJ10867; MCPH3
Tractability: Small molecule: a structure with a bound ligand is known. PROTAC: ubiquitination databases record sites on it; its protein half-life has been measured.
Gene: Protein-coding gene on chromosome 9 (120,388,875 to 120,580,172, reverse strand). Ensembl gene ENSG00000136861.
Subcellular location: Cytoplasm, cytoskeleton, microtubule organizing center, centrosome; Golgi apparatus; Cytoplasm; Cytoplasm, cytoskeleton
Subcellular location (Human Protein Atlas): Basal body; Centrosome; Cell Junctions; Cytosol; Equatorial segment; Mid piece; Principal piece
Pathways (Reactome):
Cell Cycle: AURKA Activation by TPX2; Loss of Nlp from mitotic centrosomes; Loss of proteins required for interphase microtubule organization from the centrosome; Recruitment of NuMA to mitotic centrosomes; Recruitment of mitotic centrosome proteins and complexes; Regulation of PLK1 Activity at G2/M Transition
Organelle biogenesis and maintenance: Anchoring of the basal body to the plasma membrane
Gene Ontology:
Molecular function: calmodulin binding; gamma-tubulin binding; microtubule binding; protein binding; protein kinase binding; transcription cis-regulatory region binding; tubulin binding; protein-containing complex binding
Biological process: centriole replication; centrosome cycle; chromosome segregation; microtubule bundle formation; microtubule cytoskeleton organization; microtubule organizing center organization; positive regulation of DNA-templated transcription; positive regulation of microtubule polymerization; regulation of mitotic cell cycle spindle assembly checkpoint; brain development; establishment of mitotic spindle orientation; negative regulation of centriole replication; neurogenesis; regulation of neuron differentiation; negative regulation of neuron differentiation
Cellular component: centrosome; ciliary basal body; cytoplasm; cytosol; extracellular exosome; gamma-tubulin ring complex; Golgi apparatus; microtubule; microtubule plus-end; pericentriolar material; perinuclear region of cytoplasm; spindle pole; cytoskeleton; mitotic spindle pole; microtubule organizing center
Genetic constraint (gnomAD): Loss-of-function variants: 117 observed, 197.27 expected, observed/expected ratio (o/e) 0.59, 90% interval 0.51 to 0.69. The upper end of that interval is the gene's LOEUF score, 0.69, which puts it in group 2 of 6, group 1 being the genes least tolerant of losing a copy. Missense variants: 1,915 observed, 2,057.2 expected, observed/expected ratio (o/e) 0.93, 90% interval 0.9 to 0.97. Synonymous variants: 737 observed, 791.25 expected, observed/expected ratio (o/e) 0.93, 90% interval 0.88 to 0.99.
Gene-disease validity (ClinGen):
ClinGen rates the evidence that CDK5RAP2 causes each of these diseases.
autosomal recessive primary microcephaly (autosomal recessive): Definitive. Autosomal recessive primary microcephaly (MCPH) is a rare genetically heterogeneous disorder of neurogenic brain development characterized by reduced head circumference at birth with no gross anomalies of brain architecture and variable degrees of intellectual impairment.
Homologues: Orthologues: chimpanzee CDK5RAP2 (97% identical), macaque CDK5RAP2 (94% identical), pig CDK5RAP2 (75% identical), guinea pig CDK5RAP2 (74% identical), rabbit CDK5RAP2 (73% identical), rat Cdk5rap2 (71% identical), dog CDK5RAP2 (70% identical), mouse Cdk5rap2 (68% identical), tropical clawed frog cdk5rap2 (15% identical), zebrafish cdk5rap2 (13% identical). Paralogues in human: PDE4DIP (22% identical).
Diseases named in the same sentence as CDK5RAP2 in open-access papers:
CDK5RAP2 is named in the same sentence as 48 diseases in open-access papers, as found by Europe PMC text mining. Sharing a sentence is not in itself a finding about the gene and the disease. The quoted sentences say what the papers report.
microcephaly (69 papers, 2007 to 2025). A congenital or acquired developmental disorder in which the circumference of the head is smaller than normal for the person's age and sex. "It was observed that a heterozygous mutation in the CDK5RAP2 gene leads to premature neural differentiation and microcephaly utilizing primary microcephaly patient-derived organoids." (PMID 38928228, 2024). "Firstly, we analyzed a primary microcephaly condition due to a loss-of-function homozygous mutation in a centrosome protein CDK5RAP2." (PMID 39702477, 2024). "Homozygous inactivating mutations of CDK5RAP2 underlie human congenital primary microcephaly with reduced cerebral cortex growth." (PMID 36997626, 2023). "For example, an organoid model of microcephaly associated with CDK5RAP2 mutation showed a significantly reduced size and smaller number of progenitors undergoing premature neurogenesis, similar to observations in patients." (PMID 37569905, 2023). "For example, mouse models of microcephaly associated CDK5RAP2 disease requires a complete knockout of CDK5RAP2 and result in apoptosis as the primary cause of neuronal progenitor cell depletion and microcephaly." (PMID 35431798, 2022). "Among the genes known to be associated with microcephaly, CDK5 regulatory subunit-associated protein 2 (CDK5RAP2) regulates the replication process of centrosome proteins, and loss or mutation of CDK5RAP2 can cause microcephaly disease." (PMID 36506083, 2022). "Conversely, a patient-derived CO model containing a heterozygous truncating mutation in the CDK5RAP2 gene recapitulated severe microcephaly and resulted in fewer neurons and smaller progenitor zones." (PMID 35431798, 2022). "Research has also demonstrated that centrosome activity is more fundamental for the development of brain tissue than for any other tissue by associating CDK5RAP2 gene disruption with microcephaly and ZIKV congenital infection." (PMID 33815457, 2021). "They reprogrammed fibroblasts with heterozygous truncating mutations in CDK5RAP2 obtained from a microcephaly patient to be human iPSCs as the source of a patient-derived microcephaly organoid model." (PMID 33888112, 2021). "PDE4DIP has been identified as a putative target for brain-enriched miRNA, where PDE4DIP is a homolog of CDK5RAP2, a gene that has been linked to microcephaly." (PMID 32787845, 2020). "Cerebral organoids have been shown to mimic clinical conditions of abnormal head size in infancy and childhood, including microcephaly, in patients with CDK5RAP2 mutations and Zika infection and megacephaly, in autism spectrum disorders." (PMID 29358305, 2018). "CDK5RAP2 is one of the primary microcephaly genes that are associated with reduced brain size and mental retardation." (PMID 26550838, 2015). "One current model for the microcephaly phenotype of CDK5RAP2 mutations invokes a premature shift from symmetric to asymmetric neural progenitor-cell divisions with a subsequent depletion of the progenitor pool and a reduction of the final number of neurons." (PMID 26322982, 2015). "Common features of patients with CDK5RAP2 mutations include microcephaly from birth (−4 to −8 SDS), with mild-to-moderate learning disability." (PMID 22887808, 2012). "To test whether other structural proteins are affected by reduced MLL levels, we stained and quantified CDK5RAP2, another microcephaly-associated structural component of PCM." (PMID 39661677, 2024). "Hi-Q brain organoids could recapitulate the phenotypes of both primary microcephaly due to a mutation in the centrosomal protein CDK5RAP2 and the neurological phenotype of progeria-associated Cockayne syndrome due to DNA damage." (PMID 39702477, 2024). "When modeling CDK5RAP2-mutated microcephaly, Hi-Q brain organoids could recapitulate the premature differentiation of NPCs, a mechanism attributed to causing the depletion of NPCs causing microcephaly." (PMID 39702477, 2024).
microcephaly (continued). "Mutations in the CDK5RAP2 gene could affect the neocortical progenitor cells and have been reported in patients with microcephaly." (PMID 29937727, 2018). "Interestingly, cerebral organoids derived from a microcephaly patient with a truncating mutation in CDK5RAP2, exhibited premature neural differentiation, a defect that reflects the disease phenotype." (PMID 29937727, 2018). "Primary microcephaly with CDK5RAP2 mutation and Zika virus infection were studied by cerebral organoid culture suggests that 3D culture could recapitulate real in vivo organ development to some extent." (PMID 29058117, 2017). "Moreover, in mice, loss-of-function mutations in CDK5RAP2, the causative gene for the inherited disease MCPH3, resulted in the microcephaly phenotype, and CDK5RAP2-mutant mouse embryonic fibroblasts showed centrosome overduplication." (PMID 27367050, 2016). "Moreover, mutations in human Cdk5Rap2/Cnn have been implicated in microcephaly, a pathology linked to a failure in neural progenitor cell proliferation, although the precise reason for this is unclear." (PMID 25149451, 2014). "One current model for the microcephaly phenotype caused by CDK5RAP2 mutation invokes a premature shift from symmetric to asymmetric neural progenitor cell divisions with a subsequent depletion of the progenitor pool and a reduction in the final number of neurons, and decreased cell survival." (PMID 23587236, 2013). "MCPH3 is a very rare neurodevelopmental disorder caused by biallelic variants in the CDK5RAP2 gene and is characterized by severe microcephaly, speech delay, learning disabilities, sensorineural hearing loss, and cutaneous pigmentary abnormalities." (PMID 41153337, 2025). "This is further supported by the fact that many genes associated with microcephaly encode centrosome proteins (CPAP, CEP152, CEP135, STIL, and CDK5RAP2) involved in centriole biogenesis and centrosome maturation." (PMID 39412222, 2025). "Genetic mutations in centrosome-associated proteins like CDK5RAP2 and abnormal spindle-like, microcephaly-associated (ASPM) lead to microcephaly." (PMID 39661677, 2024). "Human-specific SVAs in microcephaly CDK5RAP2 and epilepsy SCN8A gene introns repress their expression via transcription factor ZNF91 to delay neuronal maturation." (PMID 36997626, 2023). "We first focused on CDK5RAP2 because of its major role in human microcephaly and requirement during neurogenesis, its human-specific tandem SVA_F, and its strong downregulation with AK057321 loss." (PMID 36997626, 2023). "Over-expressing SVA-lncRNA AK057321 or deleting ZNF91, each independently, increases CDK5RAP2 gene expression, a microcephaly gene with an intronic human-specific SVA_F that increases during neuronal maturation." (PMID 36997626, 2023). "All common mutations causing microcephaly are present in genes implicated in cell division (MCPH1, ASPM, CDK5RAP2, CENPJ, STIL, WDR62, and CEP152)." (PMID 37294214, 2023). "CDK5RAP2, which encodes the CDK5 regulatory subunit-associated protein 2, was the first gene used to study microcephaly in brain organoids." (PMID 36340790, 2022). "We also examined the expression of other microcephaly-related genes: Mcph1, Cdk5rap2, and Aspm that were involved in germ cell maintenance, but we did not detect significant differences in their mRNA expression with WDR62 deficiency." (PMID 34059773, 2021). "In neurons, loss of CDK5RAP2 reduced Hippo-dependent YAP/TAZ signaling, possibly affecting cell proliferation which would explain CDK5RAP2-dependent microcephaly." (PMID 34685637, 2021). "Mice with an in-frame deletion in CDK5RAP2 show microcephaly and proliferative and survival defects in neurons during development." (PMID 28740121, 2017). "In other cases, such as for example when CDK5RAP2, CENPJ, and PLK4 are mutated, microcephaly seems to be the product of an increased cell death affecting both the progenitor and neuronal populations, due to mitotic delay and/or aneuploidy." (PMID 25729350, 2015).
microcephaly (continued). "In an effort to identify an appropriate model to further investigate CDK5RAP2 and primary microcephaly, we sought to perform a comparative analysis of CDK5RAP2 expression in rat and mouse." (PMID 26550838, 2015). "Of the eight known microcephaly genes, one (CDK5RAP2) is situated within the candidate region on chr9q33.1–q34.12." (PMID 22887808, 2012). "We predict that defects in TUBGCP6, CDK5RAP2 and CENPJ cause primary microcephaly by similar mechanisms." (PMID 22279524, 2012). "CDK5RAP2 is a gene that regulates CDK5, and when mutated, causes microcephaly." (PMID 37808474, 2023). "This microcephaly-like phenotype was unlikely an artificial effect of cell line discrepancies, as the reduced organoid size could be rescued by CDK5RAP2 overexpression, and could be reproduced by RNAi-mediated knockdown of CDK5RAP2." (PMID 34982276, 2022). "Mutations in microcephaly genes like assembly factor for spindle microtubules (ASPM), CDK5 regulatory subunit associated protein 2 (CDK5RAP2), microcephalin 1 (MCPH1), and centromere protein J (CENPJ) underwent pervasive positive selection during human evolution." (PMID 36550402, 2022). "Astrin is a component of centriolar satellites in interphase, and it is required for the centrosomal localization of CDK5RAP2, a protein involved in microcephaly, and for proper centriole duplication in S phase, a step which is crucial for cell cycle progression." (PMID 35559794, 2022). "Before neurogenesis, the neural progenitor cells of mice do not continue to proliferate and expand as humans do, which explains that CDK5RAP2 deficient mice do not show the same microcephaly as humans." (PMID 36118578, 2022). "The observation that mutations in CEP135, CDK5RAP2/CEP215 and NIN can lead to microcephaly raises the interesting question of whether CEP250 defects also affect brain development?" (PMID 36285440, 2022). "Additionally, the digenic inheritance of CDK5RAP2 and CEP152 heterozygous mutations causes Seckel syndrome, a disease which includes microcephaly as a clinical feature." (PMID 33178111, 2020). "Strikingly, most mouse models of microcephaly where the candidate genes (CDK5RAP2, CPAP, ASPM, Wdr62, and Plk4) were either completely ablated or highly overexpressed have invariably displayed apoptosis as a prominent mechanism for causing NPCs depletion and microcephaly." (PMID 32457578, 2020). "We observed one single m6A site near the stop codon in 7 microcephaly-related E-SMRs, including Brca2, Cep152, Ddx11, Nde1, Kif14, Stil and Cdk5rap2, 3 polymicrogyria-related E-SMRs (Eomes/Tbr2, Pax6 and Foxp2), and 3 megalencephaly-related E-SMRs (Gli3, Ccnd2 and Kif7)." (PMID 32992647, 2020). "We hypothesize that microcephaly-associated mutation of CEP90 causes defective centriole duplication, similar to depletion of CEP90 or of MCPH proteins such as CDK5RAP2, CEP152, WDR62 or CEP63." (PMID 26297806, 2015). "Many genes have been implicated in the development of microcephaly (summarized inTable 1) includingASPM,MCPH1,CDK5RAP2,CEP152,CENPJ,WDR62,STIL,CASC5,CEP135,ZNF335,PHC1,CDK6, with many of them contributing to centrosome and spindle protein dysfunction during mitosis." (PMID 26535115, 2015). "Their data also suggest that mouse neural progenitors prior to neurogenesis do not proliferate and expand to the same degree as in humans which might explain why CDK5RAP2-deficient mice do not exhibit microcephaly with the same severity as humans." (PMID 28822354, 2017). "We were able to attribute the lack of an obvious microcephaly phenotype in these mice at least partially to previously unknown splice variants of the Cdk5rap2 gene that are expressed in both mutant and wild-type mice." (PMID 26322982, 2015). "Further analysis, initiated on account of a lack of a microcephaly phenotype in these mutant mice, revealed the presence of previously unknown splice variants of the Cdk5rap2 gene that are at least in part accountable for the lack of microcephaly in the mice." (PMID 26322982, 2015).
microcephaly (continued). "Infratentorial anomalies such as cerebellar hypoplasia, with or without an enlarged posterior fossa, have been described, especially in ASPM-, CDK5RAP2-, and WDR62-related microcephaly." (PMID 35456440, 2022). "A number of microcephaly genes have been identified, including ASPM, microcephalin/BRIT1, CDK5RAP2/Cep215, CENPJ/CPAP, SIL/STIL, WDR62, and NDE1 (refs 3, 4, 5)." (PMID 27553190, 2016). "Using phylogenetically corrected comparative analyses, we find that the evolution of two microcephaly loci, ASPM and CDK5RAP2, are correlated with neonatal brain size in Glires and Euungulata, the two most densely sampled non-primate clades." (PMID 24898820, 2014). "This is not surprising as several of the key primary microcephaly genes (CDK5RAP2, ASPM, WDR62, and MCPH1) are essential for the control of mitosis and cell cycle progression." (PMID 36845425, 2023). "However, these mutant cells responded differently from cells with an intact ASPM gene to RNAi against CDK5RAP2/CEP215, a cnn ortholog responsible for human microcephaly." (PMID 36980263, 2023). "Although CDK5RAP2 is traditionally established as a “non-syndromic MCPH gene”, the presence of further anomalies in these patients is more consistent with the criteria of syndromic microcephaly." (PMID 36831309, 2023). "CDK5RAP2 is expressed in neural progenitor cells; mutant mice lacking CDK5RAP2 exhibit mild microcephaly." (PMID 33946187, 2021). "To determine whether estradiol could regulate the seven currently known microcephaly genes (ASPM, CENPJ, CEP152, CDK5RAP2, MCPH1, STIL and WDR62), we conducted a search of the potential ERE (estrogen response element) sites in gene promoter regions." (PMID 26123139, 2015). "Notably, both MCPH3/Cdk5rap2 and MCPH5/Aspm-null mice exhibited microcephaly at birth, and the degrees of reduction of the brain sizes of those mutant mice are comparable to our Zfp568fx/fx;Nes-cre mice." (PMID 23071813, 2012). "Our study confirms CDK5RAP2 is a rare primary microcephaly disease gene and emphasizes that when no consanguinity is reported but is suspected, SNP-array testing can reveal cnLOH that may infer distant relationships between parents and guide disease gene identification." (PMID 22887808, 2012). "The most common primary (not involved with other syndromes) microcephaly genes are WDR62, ASPM, MCPH1, CDK5RAP2, STIL, CEP152." (PMID 37808474, 2023).